ENSG00000256591 (novel transcript)
Gene: Protein-coding gene on chromosome 11 (61,429,220 to 61,485,822, forward strand). Ensembl gene ENSG00000256591.
Genetic constraint (gnomAD): Loss-of-function variants: 16 observed, 13.82 expected, observed/expected ratio (o/e) 1.16, 90% interval 0.78 to 1.72. Missense variants: 173 observed, 172.77 expected, observed/expected ratio (o/e) 1, 90% interval 0.88 to 1.14. Synonymous variants: 71 observed, 65.17 expected, observed/expected ratio (o/e) 1.09, 90% interval 0.9 to 1.33.